UNC5B (unc-5 netrin receptor B)
Diseases named in the same sentence as UNC5B in open-access papers (continued):
Sharing a sentence is not in itself a finding about the gene and the disease.
tumor (40 papers, 2007 to 2025). "Furthermore, we observed that DAC treatments were associated with the re‐expression of DAPK1, netrin‐1, and UNC5B by the IHC staining of tumor sections." (PMID 27378792, 2016). "The results showed that the expression level of UNC5B in tumor tissues was significantly higher than that in adjacent normal tissues." (PMID 35035481, 2022). "Meanwhile, tumor weight test results showed that tumor weight decreased after silencing UNC5B compared with the sh-NC group." (PMID 35035481, 2022). "On the contrary, the intracellular domains of UNC5B promote cell proliferation in vitro and tumour formation in vivo, by binding a large number of ribosomal proteins." (PMID 33345442, 2021). "By contrast, full‐length UNC5B slightly decreased the tumour volume by largely mediating cell cycle arrest, which was identical to our previous study." (PMID 33345442, 2021). "In order to clarify the effect of UNC5B truncates and full‐length UNC5B on tumour metastasis, we also established animal models of tail vein injection in 16 mice." (PMID 33345442, 2021). "EDU assay, apoptosis, xenograft tumour implantation, migration, invasion and tumour metastasis were performed to comprehensively identify the effects of UNC5B truncates on BC cells." (PMID 33345442, 2021). "We observed that the overexpression of UNC5B truncates in 5637 cells significantly increased the tumour volume on mice." (PMID 33345442, 2021). "And the mean beta values of UNC5B were at a very low level, about 0.10, in both normal and tumor tissues." (PMID 34922605, 2021). "In view of the reports of spectrin in impacting tumour development and aggressiveness, the binding of spectrin family to the intracellular domain of UNC5B was also considered to be closely related to the metastasis of BC cells." (PMID 33345442, 2021). "According to EC-restricted NOVA2 expression in cancer specimens, we found that UNC5B-Δ8 was present only in the tumor endothelium." (PMID 34381052, 2021). "We demonstrate that the intracellular domain of UNC5B promotes cell proliferation and tumour formation, by binding to a large number of ribosomal proteins." (PMID 33345442, 2021). "The Netrin-1 receptor UNC5B is an axon guidance regulator that is also expressed in endothelial cells (ECs), where it finely controls developmental and tumor angiogenesis." (PMID 34381052, 2021). "Although the molecular mechanisms regulating UNC5B-mediated apoptosis are still poorly known, they are fundamental to understand important aspects of developmental as well as tumor angiogenesis." (PMID 34381052, 2021). "The transmembrane protein uncoordinated‐5 homolog B (UNC5B) is verified to inhibit cell proliferation in some types of tumours." (PMID 33345442, 2021). "We demonstrate that the intracellular domain of UNC5B promotes cell proliferation in vitro and tumour formation in vivo, by binding to a large number of ribosomal proteins." (PMID 33345442, 2021). "Among the tumor suppressor genes frequently epigenetically downregulated in CRC, the four related genes of the UNC5 family: UNC5A, UNC5B, UNC5C and UNC5D encode dependence receptors that regulate the apoptosis/survival balance." (PMID 33126652, 2020). "UNC5B expression in 5637 and 5637-U cells and mice tumor specimens derived from these cell lines was analyzed by immunohistochemistryand western blotting." (PMID 27846823, 2016). "UNC5B protein expression was localized to both the cytoplasm and the nuclear membranes in the tumor tissues." (PMID 27846823, 2016). "We showed that netrin-1 inhibited PDAC tumor growth by interfering with integrin β4 expression, which depends on the activation of UNC5b/FAK signaling and requires NO-mediated PP2A activation and the subsequent suppression of the MAPK pathway." (PMID 27034160, 2016).
tumor (continued). "During cancerogenesis, UNC5B is down-regulated in various kinds of tumour affecting anchorage-independent growth and invasiveness and cell survival." (PMID 24720832, 2014). "The protein expression of netrin-1 and UNC5B showed the same trend as that of mRNA expression, and the optical density of all tumor (T) & normal (N) tissues were measured and expressed graphically." (PMID 24528886, 2014). "During cancerogenesis UNC5B is downregulated in various kinds of tumor affecting anchorage-independent growth and invasiveness and cell survival." (PMID 22848430, 2012). "High expression of UNC5B enhanced tumor proliferation and metastasis." (PMID 36468399, 2023). "UNC5B has the potential to either promote or prevent tumor growth in certain tumor types." (PMID 36330451, 2022). "Since senescence is conventionally a potent tumor suppressor mechanism, UNC5B could contribute to cellular senescence." (PMID 34239689, 2021). "Furthermore, the correlation of UNC5B-Δ8 and NOVA2 expression with a tumor angiogenic signature is in line with the possibility that the NOVA2/UNC5B-Δ8 circuit plays a role also in the tumor vascular niche." (PMID 34381052, 2021). "Furthermore, our preliminary and correlative observations suggest a possible role of the UNC5B-Δ8/NOVA2 axis also in tumor angiogenesis." (PMID 34381052, 2021). "However the complete elucidation of UNC5B-Δ8 and apoptosis roles in the tumor vasculature context requires further studies." (PMID 34381052, 2021). "Kaplan-Meier plots and log-rank tests showed that patients with high netrin-1 expression and low UNC5B expression in their tumor tissues had statistically significant shorter survival rate compared with those with low netrin-1 expression and high UNC5B expression (P < 0.01)." (PMID 24528886, 2014). "Since PKC α, netrin-1and UNC5B play a significant role in the process of tumor treatment." (PMID 24528886, 2014). "Direct sequencing of the coding region and flanking intronic sequences revealed no mutations in PRF1 or in the putative tumour suppressor UNC5B." (PMID 20140240, 2010). "Hence, it is tempting to speculate that the NOVA2-driven UNC5B-Δ8 production restricted to tumor ECs, may represents a post-transcriptional mechanism favoring cancer cells dissemination." (PMID 34381052, 2021). "Furthermore, the silencing of DAPK1 or UNC5B mRNA prevented the inhibition of tumor growth induced by the combination treatment, further confirming our working hypothesis." (PMID 27378792, 2016). "In these tumors, the gain of netrin-1 or the deletion of Unc5b and DCC prevents tumor cells from undergoing apoptosis and thereby promotes tumor growth and metastases." (PMID 35008701, 2021). "The other netrin-1 receptors, UNC5A, UNC5B, and UNC5C, were also discovered as putative tumor suppressor genes in various tumors." (PMID 26207151, 2015). "Similar to DCC receptors, other netrin-1 receptors, including UNC5A, UNC5B, and UNC5C, were also discovered as putative tumor suppressor genes in various tumors, including gastric cancer." (PMID 26207151, 2015). "In addition, we have yet to examine the possible roles of other NTN1 receptors in PDAC innervation and development, despite the roles of UNC5B and DCC in neural development, tumor cell growth and EMT." (PMID 40777309, 2025). "However, further studies are required to better assess the contribution of UNC5B-Δ8 and NOVA2 to tumor vascularization and metastasis." (PMID 34381052, 2021).
tumor (continued). "However, we found that the overexpression of UNC5B truncates did not mediate apoptosis; on the contrary, it promoted proliferation and tumour formation by binding to a large number of ribosomal proteins." (PMID 33345442, 2021). "Collectively, our results strongly support a role for NOVA2 in controlling the dependence receptor function of UNC5B in ECs and suggest that the NOVA2/UNC5B axis may represents a post-transcriptional pathway relevant to both developmental and tumor angiogenesis." (PMID 34381052, 2021). "As for UNC5B, nearly no methylation alteration was observed, and CpG sites around TSS remained hypomethylated in both normal and tumor tissues." (PMID 34922605, 2021). "However, in our previous studies, the cotransfection of UNC5B and DAPK in BC cells did not cooperate to promote apoptosis, but significantly reversed the anti‐tumour effect of DAPK." (PMID 33345442, 2021). "This antibody could block Netrin-1/Unc5B interaction to inhibit Netrin-1 induced tumor cell growth but does not inhibit Netrin-1/DCC interaction, suggesting that DCC and Unc5B also could interact with different Netrin-1 motifs in the EGF2 domain." (PMID 28245592, 2017).
cancer (34 papers, 2007 to 2025). A tumor composed of atypical neoplastic, often pleomorphic cells that invade other tissues. "The protein encoded by UNC5B belongs to a group of proteins called dependence receptors (DpRs), which are involved in embryogenesis and cancer progression." (PMID 35865633, 2022). "UNC5B encodes a protein that is part of the dependence receptors (DPRs) proteins, which are said to be involved in embryogenesis and cancer progression." (PMID 32929144, 2020). "Thus, like netrin-1, unc5b might exert different functions in different malignant tumors, and the underlying mechanism needs further investigation." (PMID 35974411, 2022). "Netrins are considered protumorigenic, but knockout and peptide/decoy receptor blocking assays reveal that in YAPoff cancers, UNC5B and Netrin-1 can cooperate with integrin-αV/β5 to mediate YAP-induced cytostasis." (PMID 39172021, 2024). "Here, using clustered regularly interspaced short palindromic repeats (CRISPR) screens, we link the Netrin receptor UNC5B to YAP-induced cytostasis in YAPoff cancers." (PMID 39172021, 2024). "A separate study on the same cancer highlighted UNC5B’s role in cell migration, invasion, and metastasis by interacting with key migration markers such as fibronectin, beta-catenin, and vimentin." (PMID 39456519, 2024). "In cancer cells, this positive feedback activation loop between AGAP2 and Akt enhances AGAP2 phosphorylation and promotes its association with UNC5B, thereby inhibiting the UNC5B-dependent programmed cell death." (PMID 36611866, 2022). "The interaction between netrin and its receptor, UNC5B, maintained cancer stemness through the crosstalk between cancer cells and CAFs." (PMID 33050237, 2020). "Here we first unravel NTN1 and its receptor UNC5B as the key downstream targets of Naa10 in cancer cell line." (PMID 27910960, 2016). "According to our results, the expression of UNC5B in metformin-aspirin treated cells is up-regulated to 11 folds compared to untreated cells, indicating a possible role of UNC5B in the anti-cancer effect induced by the combination of metformin and aspirin." (PMID 26294325, 2015). "Netrin-1 and its receptor UNC5B play important roles in angiogenesis, embryonic development, cancer and inflammation." (PMID 24528886, 2014). "Ectopic YAP expression also upregulates UNC5B relatives and their netrin ligands in YAPoff cancers." (PMID 39172021, 2024). "Thus, we studied the extent to which Netrin-UNC5B signaling is required for YAP-induced cytostasis across various YAPoff cancers." (PMID 39172021, 2024). "However, additional detailed studies must be conducted to determine how MCA induces the upregulation of UNC5B in cisplatin-resistant BEL-7404 cancer cells." (PMID 32676451, 2020). "We further analyzed the UNC5B expression in 32 cancer types utilizing the TCGA database." (PMID 32902412, 2020). "In addition, UNC5B has also been indicated as a putative tumor suppressor gene in numerous cancers, including colorectal, ovary, uterus, stomach, lung or kidney cancers." (PMID 27910960, 2016). "For example, genes that encode DRs such as DCC, neogenin, UNC5B, UNC5C, or TrkC are repressed in multiple cancer types, while cancer cells can also escape DR‐mediated apoptosis through autocrine overexpression of ligands including DKK1, Netrin‐1, NT‐3, Sema3E, or HGF." (PMID 34542930, 2021). "Forced YAP expression induced the expression of UNC5B and the related UNC5 family receptors, UNC5C and D, as well as their ligand NTN1/Netrin-1 in YAPoff cancers." (PMID 39172021, 2024). "As already described, cancer cells in cocultures with CAF upregulate the production of this ligand and UNC5B." (PMID 36587397, 2023).
cancer (continued). "Netrin-1 has been reported to act as a novel promotor of cancer cell survival and invasiveness by inhibiting apoptosis through its receptors, such as DCC, Unc5 homologues (Unc5a, Unc5b, Unc5c and Unc5d) and Neo1." (PMID 35974411, 2022). "In human cancer cells, enforced expression of UNC5A, UNC5B and UNC5C inhibits cell-anchorage growth and invasion in a way related to their pro-apoptotic activity." (PMID 33126652, 2020). "UNC5A, UNC5B and UNC5C, which are the receptors of netrin 1, are all down-regulated in various cancers through promoter methylation." (PMID 26294325, 2015). "Next, we examined the extent to which UNC5B is induced following forced YAP expression and/or constitutively expressed in YAPoff cancers, and whether induction is dependent on TEAD." (PMID 39172021, 2024). "High NTN-1 signalling through UNC5B and DCC during tumorigenesis has been related to cancer cell proliferation and migration by up-regulation of the proto-oncogene YAP, a downstream signalling of the Hippo pathway, important in cell proliferation and apoptosis." (PMID 36831381, 2023). "Although YAP-induced UNC5 and NTN mRNAs in multiple YAPoff cancer lines, and we confirmed that YAP or TEAD-VP64 induced UNC5B protein across multiple lines, we were unable to confirm whether other UNC5 proteins or NTN1 protein were induced in lines in which their mRNAs were upregulated." (PMID 39172021, 2024). "Moreover, forced overexpression of UNC5B in the kidney epithelial cells does not induce apoptosis whereas overexpression in several cancer cells induced apoptosis." (PMID 24720832, 2014). "Although previous studies suggested that NTN1 promotes cancer cell growth and EMT through the UNC5B receptor, we found that NEO1, rather than UNC5B, was largely upregulated during mouse pancreatic tumorigenesis." (PMID 40777309, 2025). "Induction of UNC5-family and NTN1 in YAPoff cancers depended on YAP/TEAD-binding as YAPS94A, which cannot bind TEADs, failed to induce UNC5B, and a TEAD4(DBD)-VP64 fusion mimicked the effects of YAP." (PMID 39172021, 2024).
infection (2 papers, 2014 to 2022). The state of being infected such as from the introduction of a foreign agent such as serum, vaccine, antigenic substance or organism. "Following infection with the UNC5B-targeting lentivirus, UNC5B expression was measured in REH cells and SUP-B15 cells by western blotting." (PMID 35974411, 2022). "The effects of targeting UNC5B with RNAi on UNC5B expression were investigated by infection of UNC5B shRNA or scrambled shRNA control in retinas of OIR mice." (PMID 25149138, 2014). "As shown in the present study, UNC5B expression decreased dramatically following UNC5B shRNA infection, and retinal neovascularization was clearly reduced by UNC5B shRNA infection." (PMID 25149138, 2014).
bone disorder (1 paper, 2024). "Regarding the interaction between netrin-1 and DCC or UNC5 in bone disorders, netrin-1 is highly expressed in the synovial fluid of rheumatoid arthritis patients, and activation of the netrin-1/UNC5B axis has been shown to prevent bone destruction." (PMID 38628640, 2024). "Regarding their roles in bone disorders, UNC5B, as a downstream effector of netrin-1, has been shown to prevent bone destruction, and DCC has been reported to be expressed in a CD166-positive subpopulation of chondrocytes in human osteoarthritic cartilage." (PMID 38628640, 2024). "Thus, the specific modulation of DCC and UNC5B via netrin-1 may serve as a promising strategy to treat bone disorders." (PMID 38628640, 2024).
kidney disease (1 paper, 2014). "Development of netrin-1 based therapies or small molecule that can activate its receptor UNC5B will be able to treat not only kidney disease but also the inflammatory disease of other organs as well." (PMID 24991088, 2014).
neurodegenerative disease (1 paper, 2023). A disorder of the central nervous system characterized by gradual and progressive loss of neural tissue and neurologic function. "While UNC5B has not been implicated as an ALS gene, signaling downstream of UNC5 may contribute to axonal retraction and/or synaptic phenotypes in neurodegenerative disease." (PMID 37039476, 2023).
neurological disorders (1 paper, 2022). "Anti-Unc5B mAbs could therefore synergize with existing therapies such as focused ultrasound/microbubble approaches and offer a therapeutic perspective for treatment of various human neurological disorders." (PMID 35246514, 2022). "We show that intravenous delivery of monoclonal antibodies blocking Netrin-1 binding to Unc5B induce transient BBB opening to bioactive molecules, which could be useful for drug delivery in various neurological diseases." (PMID 35246514, 2022).
vascular disorder (1 paper, 2021). A general term used to describe any disease affecting blood vessels]. "Therefore, inhibiting UNC5B might reduce endothelial cell senescence and hinder age-related vascular disorders." (PMID 34239689, 2021).
UNC5B also shares sentences with these, for which no sentence is quoted: medulloblastoma (3 papers); acute myeloid leukemia (2); breast ductal carcinoma (2); Insulin resistance (2); renal carcinoma (2); angina (1); bladder tumor (1); breast tumors (1); cholangiocarcinoma (1); epilepsy (1); glioblastoma (1); heart failure (1); hematoma (1); intracranial aneurysm (1); invasive ductal breast carcinoma (1); iron deficiency (1); ischemic stroke (1); lobular breast carcinoma (1); multiple sclerosis (1); nasopharyngeal carcinoma (1); neuroblastoma (1); Ogden syndrome (1); prostate tumors (1); psychiatric disorder (1); retinopathy of prematurity (1); serous ovarian cancer (1); Stroke (1); thymoma (1); urothelial carcinoma (1).